GAPDH (glyceraldehyde-3-phosphate dehydrogenase)
Diseases named in the same sentence as GAPDH in open-access papers (continued):
Sharing a sentence is not in itself a finding about the gene and the disease.
lung carcinoma (continued). "The results of RT-PCR using GAPDH as a reference gene indicated that the mRNA expression levels of HSDL2 in human lung cancer cell lines were significantly higher than that in human lung epithelial cell line." (PMID 32211805, 2020). "Quantitatively, real-time PCR analysis further revealed that ΔCt references relative to GAPDH of LINC00173.v1 were differentially lower than those of LINC00173.v2 in lung cancer tissues and cell lines respectively." (PMID 32473645, 2020). "The two systems were tested on the basis of expression levels of the genetic markers vimentin, E-cadherin, N-cadherin and GAPDH in A549 lung carcinoma cells at two known concentrations." (PMID 29467444, 2018). "Recent studies have established enhanced expression of both mRNA and protein level of GAPDH in human lung cancer tissues, pancreatic adenocarcinomas, and dunning rat prostate cancer cell lines compared with normal tissues and cell lines." (PMID 26911935, 2016). "Still, some reports support GAPDH as an excellent reference gene in hypoxic hepatocellular, colonic and lung carcinoma models." (PMID 27835695, 2016). "In lung cancer, GAPDH protein is well known to be over expressed as compared to normal lung tissue, and GAPDH gene is known to be expressed at high levels as compared to the surrounding non cancerous lung biopsies." (PMID 23988223, 2013). "The relative mRNA level of the cav-1 gene (cav-1 per GAPDH, mean ± SD) showed significant differences between lung cancer tissue (1.146±0.167) and the surrounding normal lung tissue (3.254±0.248)." (PMID 22200856, 2012). "Using a different method than reported here, a study found that GAPDH was the most stable reference gene in the bronchoalveolar samples of people with nonsmall cell lung cancer." (PMID 21272375, 2011). "Our data suggest that both GAPDH and β-actin have a significantly increased expression in lung cancer samples." (PMID 19890392, 2009). "Recent lung cancer molecular profiling studies have employed a group of widely used endogenous control genes, such as GAPDH, beta-actin (ACTB), TATA-binding protein (TBP), 18s-rRNA, HMBS and phenylalanine hydroxylase, for RT-PCR." (PMID 19014639, 2008). "Most lung cancer qPCR studies use commercial RGs, such as glyceraldehyde-3-phosphate dehydrogenase (GAPDH), β-actin (ACTB), TATA-binding protein, β-microglobulin, cytochrome oxidase II, 18S ribosomal RNA (rRNA18S)." (PMID 16872493, 2006). "Furthermore, mRNA expression of RRM2 and GAPDH was assessed in three lung cancer cell lines (A549, NCI-H1395, and NCI-H1975) and normal lung epithelial cells (BEAS-2B) via RT-PCR, reinforcing the role of these prognostic genes in LUAD." (PMID 40341308, 2025). "In AKT1 (r = −0.15, p < 0.05), BRAF (r = −0.25, p < 0.05), GAPDH (r = −0.3, p < 0.05), KRAS (r = −0.24, p < 0.05), MYC (r = −0.25, p < 0.05), and SRC (r = −0.24, p < 0.05), stromal score was negatively correlated with lung cancer and the highest correlation coefficient was in GAPDH." (PMID 39734333, 2024). "However, studies have shown that GAPDH, GUSB, and β-2 M were detected using qRT-PCR in 20 cases of lung cancer tissue and adjacent normal tissue, and the largest differences within and between groups were found in GAPDH." (PMID 38711158, 2024). "The expression of FLNA was significantly higher in lung cancer patients than in normal people, indicating that GAPDH can be used as a reference gene for RT-qPCR analysis of tumor platelets, and also had a profound clinical application value for the early diagnosis of cancer." (PMID 35770000, 2022). "Additionally, a study indicated that BACH1 bound to the glycolytic gene Hexokinase 2 (HK2) and Glyceraldehyde-3-Phosphate Dehydrogenase (GAPDH) promoters, activated their expression and stimulated glycolysis rate, thereby promoting metastasis in lung cancer." (PMID 34351577, 2022). "GAPDH could be utilized as a reference gene for normalizing lung cell lines, while it was de-regulated in non–small cell lung cancer specimens." (PMID 35711943, 2022).
lung carcinoma (continued). "Compared to normal lung tissue, GAPDH in both mRNA and proteins levels were upregulated in lung cancer tissue, which might contribute to the increased “aerobic glycolysis”." (PMID 32140187, 2020). "Likewise, glyceraldehyde-3-phosphate dehydrogenase and hexokinase 1 genes were up-regulated by > 3-fold in PLACs and were also reported to be up-regulated in human lung cancers." (PMID 27602772, 2016). "Moreover, depletion of GAPDH with RNA interference in human lung carcinoma A549 and UO31 cells stopped cell proliferation, and induced cell cycle arrest in G1 phase, which is in accordance to severe inhibition of the enterance into S phase reported here." (PMID 26017754, 2015). "Activation of glycolysis in human lung cancers and cancer cells was inferred from an up-regulation of glycolysis-related enzymes such as hexokinase II (HK II), glyceraldehyde-3-phosphate dehydrogenase (GAPDH), and the bifunctional regulatory enzyme phosphofructokinase 2 (PFK-2)." (PMID 19558692, 2009). "Moreover, IHC expression profiles for β-actin and GAPDH, assessed in the Human Protein Atlas, were highly variable in lung cancer samples." (PMID 19890392, 2009). "Furthermore, BACH1 activates the transcription of HK2 (Hexokinase 2) and GAPDH (glyceraldehyde-3-phosphate dehydrogenase), enhancing glucose uptake, glycolytic flux, and lactate secretion, thereby promoting lung cancer metastasis through a glycolysis-dependent pathway." (PMID 40847302, 2025). "However, the precise regulatory mechanism of GAPDH in ferroptosis remains veiled, hence, meticulous exploration into its specific function and mechanism could unveil new vistas for lung cancer treatment." (PMID 38515565, 2024). "Despite the elevated expression of GAPDH in lung cancer, its manifestation is significantly reduced in ferroptosis scenarios, implying that with the uptick in immune checkpoint protein expression during ferroptosis, tumor cells might navigate immune surveillance more adeptly." (PMID 38515565, 2024). "The top 10 proteins (MIG6, GAPDH, NDRG1_pT346, BRD4, CD26, TFRC, INPP4B, GSK3ALPHABETA, IGFBP2, and DUSP4) were screened by applying the WBFS algorithm, and they can be regarded as the candidate biomarkers that are most closely associated with the classification of lung cancer subtypes." (PMID 37509950, 2023). "Furthermore, the in vitro drug-sensitivity in cell lines would suggest that PGC-1alpha and GAPDH/MT-CO1 levels could be used to predict patient response to treatments based on targeting glucose metabolism on lung cancer." (PMID 29192176, 2017). "However, GAPDH expression in lung cancer is highly variable." (PMID 19890392, 2009). "BACH1 activates the transcription of glycolytic enzymes hexokinase 2 (HK2) and GAPDH, thus increasing glucose uptake, glycolysis rates, and lactate secretion to promote KRAS-driven lung cancer metastasis." (PMID 39061897, 2024). "The relative expression of FAS in lung cancer cell lines (H1299, H1993, A549) was significantly lower than the normal bronchial epithelial cell line (HBE), with GAPDH serving as the internal control." (PMID 39416461, 2024). "In immunohistochemistry experiments, the expression levels of multiple genes, including CHCHD2, CEACAM5, GAPDH, and CD24, were significantly upregulated in lung cancer tissues compared to normal tissues." (PMID 38872167, 2024). "Lung cancer cells were treated with 0–50 μM artonin F for 24 h, and the results showed that the ratios of PI3K, Akt, mTOR to GAPDH were reduced in cells treated with artonin F at the concentrations that induced apoptosis." (PMID 35631459, 2022). "The expressions of GAPDH in colon cancer, PTMA in healthy control, and GNAS in non–small-cell lung cancer were also higher." (PMID 35770000, 2022). "TUBA1C, GAPDH, KRT25, GCC2, and POTEKP were the five proteins identified as potential lung cancer-specific exosome biomarkers." (PMID 34771645, 2021).
lung carcinoma (continued). "Our mouse model was injected with human H460-hCD63-GFP lung cancer cells, which subsequently produced species-specific CD63 proteins and GAPDH mRNA, the very markers we detected and reported in blood and saliva." (PMID 25397880, 2014). "Considering results from both softwares, PPIA, RPLPO, GAPDH, HPRT1, and 18S can be considered accurate reference genes in lung cancer cell lines." (PMID 19014639, 2008). "Mechanistically, these antioxidants stabilize HK2 and glyceraldehyde 3-phosphate dehydrogenase (GAPDH) expression, enhance glucose uptake, increase glycolytic rates and stimulate lactate secretion, thereby facilitating glycolysis-responsive lung cancer development." (PMID 39806421, 2025). "Notably, our study identified a negative correlation between the expression of key hub genes (AKT, BRAF, GAPDH, KRAS, MYC, and SRC) and immune and stromal cell content in the lung cancer TME." (PMID 39734333, 2024). "Furthermore, SIRT5-catalyzed removal of GAPDH malonylation enhances its enzymatic activity, while SIRT5 KO reduces lung cancer cell growth in vitro and in vivo." (PMID 36818560, 2023). "The GAPDH gene was more stable in colon cancer, and the GNAS gene was highly stable in lung cancer." (PMID 35770000, 2022). "Moreover, hexokinase 2 (HK2) and glyceraldehyde-3-phosphate dehydrogenase (GAPDH) have been identified among the strongest transcriptional targets of BACH1, suggesting that BACH1 stimulates glycolysis in lung cancer." (PMID 33499022, 2021). "For example, in lung cancer, BACH1 activates the transcription of Hexokinase 2 and GAPDH, enhances the uptake of glucose of cancer cells, improves the glycolysis, and alleviates oxidative stress-induced damage of cancer cells, hence facilitating cancer cell metastasis." (PMID 34191748, 2021). "In conclusion, GAPDH gene expression level in resected tumor, as assessed by RQ-PCR or microarray, is an important prognostic factor in NSCLC, that confirms the importance of investigating metabolism in lung cancer." (PMID 23988223, 2013). "We cannot exclude the possibility that our findings with GAPDH were not due to this difference although as the tissue was taken from relatively normal lung and the subjects were in good health with early stage lung cancer we feel it is unlikely." (PMID 19133266, 2009). "Therapeutic strategies for treatment of hepatocellular carcinoma, human lung cancer or human colon involving GAPDH as target molecule do not represent a valid approach in conjunction with tumor hypoxia." (PMID 19144146, 2009). "GAPDH and HPRT1 have been recommended as suitable reference genes for lung cancer research." (PMID 19014639, 2008). "Our data are strongly in agreement with previous indication that GAPDH is regulated in response to various stimuli (i.e hypoxia, insulin, mitogen, EGF) and that its transcript is elevated in various cancer tissues, including lung cancer." (PMID 16872493, 2006). "In addition, both GAPDH KD and KA treatment increased the levels of sLG, further corroborating GAPDH as critical regulator of MG production and GLO system activity in lung cancer." (PMID 40461450, 2025). "BACH1 binds to the HK2 and Glyceraldehyde 3-phosphate dehydrogenase (GAPDH) promoters, stimulating the expression of both and several other glycolytic genes, thus increasing glucose uptake, glycolysis rate and lactic acid secretion, thereby stimulating lung cancer cell metastasis." (PMID 39991762, 2025). "Therefore, GAPDH seems not to be suitable as the housekeeping gene for lung cancer experiments." (PMID 38711158, 2024). "The GAPDH-scaled protein expression levels of UBA1 and UBA7 were compared between the exposed and non-exposed lung cancer patients, separately for the normal and tumour tissue samples." (PMID 19014429, 2008).
Hyperglycemia (56 papers, 2012 to 2025). An increased concentration of glucose in the blood. "Activation of poly-ADP-ribose polymerase 1 (PARP1) in response to hyperglycemia will cause the inhibition of glyceraldehyde-3-phosphate dehydrogenase (GAPDH) activity due to depletion of glycolytic intermediates and resulting in an accumulation of upstream metabolites." (PMID 40843204, 2025). "In addition, chronic hyperglycaemia causes inhibition of the metabolic enzymes GAPDH and PDH, which contributes to the suppression of glucose metabolism." (PMID 36376280, 2022). "We next investigated whether GAPDH inhibition alone was sufficient to cause changes in glucose metabolites and insulin secretion resembling those produced by chronic hyperglycaemia." (PMID 36376280, 2022). "Research indicates that GAPDH activity is partially suppressed due to the excessive generation of mitochondrial superoxide (O2•−) resulting from hyperglycemia." (PMID 40093018, 2025). "The specific inhibitor poly (ADP-ribose) polymerase (PARP) prevents ADP-ribose modification and hyperglycemia-induced reduction in GAPDH activity." (PMID 41155932, 2025). "Research shows hyperglycaemia triggers excessive mitochondrial reactive oxygen species (ROS) production, suppressing glyceraldehyde-3 phosphate dehydrogenase (GAPDH) activity, a crucial glycolysis enzyme." (PMID 40959494, 2025). "Hyperglycemia-induced overproduction of mitochondrial superoxide inhibits GAPDH activity, which, in turn, activates the hexosamine pathway by increasing the influx of phosphorylated glucose." (PMID 40589740, 2025). "Hyperglycemia-induced superoxide reduces the activity of the glycolytic enzyme, glyceraldehyde-3-phosphate dehydrogenase (GAPDH), by modifying the enzyme with ADP-ribose polymers, increasing levels of all glycolytic intermediates upstream of GAPD." (PMID 41155932, 2025). "Hyperglycemia and hyperlipidemia have been reported to reduce glyceraldehyde-3-phosphate dehydrogenase activity, thereby increasing the synthesis of UA." (PMID 40362772, 2025). "The hexosamine pathway is a pathogenesis of diabetic neuropathy, and it enhances the flux under hyperglycemia accompanied with a decrease in GAPDH activity." (PMID 39456870, 2024). "The inhibition of glyceraldehyde-3-phosphate dehydrogenase (GAPDH) by mitochondrial overproduction of ROS resulting from hyperglycemia increases triose phosphate levels and then promotes the generation of AGEs." (PMID 39148537, 2024). "Nevertheless, multiple studies have reported that hyperglycaemia can alter GAPDH expression in cultured cells and animal models." (PMID 36627346, 2023). "In high glucose environment, it will reduce the activity of glyceraldehyde 3-phosphate dehydrogenase (GAPDH), a key glycolytic enzyme in cell types that cause intracellular hyperglycemia." (PMID 36755923, 2023). "Our data support the idea that a glycolytic metabolite lying between glucokinase and GAPDH mediates the effect of chronic hyperglycaemia on both mTORC1 and AMPK." (PMID 36376280, 2022). "Diabetes in animals and patients decreases the activity of the key glycolytic enzyme glyceraldehyde 3-phosphate dehydrogenase in cell types that develop intracellular hyperglycemia." (PMID 35453469, 2022). "Using isolated islets and INS-1 cells, we show here that one or more glycolytic metabolites downstream of phosphofructokinase and upstream of GAPDH mediates the effects of chronic hyperglycemia." (PMID 36376280, 2022). "Our results show that chronic hyperglycaemia impairs glucose metabolism via increased levels of a glycolytic metabolite lying upstream of GAPDH." (PMID 36376280, 2022). "Taken together, our results suggest that one or more metabolites upstream of GAPDH mediate the effects of chronic hyperglycaemia on glucose metabolism." (PMID 36376280, 2022).
Hyperglycemia (continued). "Consistent with the idea that the key metabolite lies upstream of GAPDH, 48 h culture with KA, or knockdown of GAPDH, in LG-cells mimicked the effects of chronic hyperglycaemia on AMPK and mTORC1 activity." (PMID 36376280, 2022). "On the one hand, it has been reported that hyperglycemia and hyperlipidemia decrease glyceraldehyde 3-phosphate dehydrogenase activity, which in turn increases UA synthesis." (PMID 36411302, 2022). "In diabetic patients, hyperglycemia triggers mitochondrial dysfunction by reducing the functional activity of glyceraldehyde 3-phosphate dehydrogenase (GAPDH; a critical glycolytic enzyme)." (PMID 36076944, 2022). "Therefore, endothelial dysfunction is caused by hyperglycemia-induced overproduction of mitochondrial O2•− and diversion of glycolytic flux from the normal glycolytic pathway to alternative metabolic pathways due to inhibition of GAPDH activity by mitochondrial O2•−." (PMID 34439553, 2021). "Both the hyperglycemia-induced decrease inactivation of GAPDH and its poly (ADP-ribosyl) ation can be prevented by overexpression of either uncoupling protein-1 or superoxide dismutase (SOD)." (PMID 33838689, 2021). "Hyperglycemia-induced overproduction of mitochondrial O2•− partially inhibits the activity of GAPDH." (PMID 34439553, 2021). "The finding that inhibiting GAPDH activity by antisense DNA resulted in the activation of each of the major pathways induced by hyperglycemia provided further evidence for a critical role of GAPDH inhibition in hyperglycemia-induced cellular damage." (PMID 34063078, 2021). "Dampening of GAPDH activity has been demonstrated as a critical step for hyperglycemia-induced vascular damage." (PMID 31133884, 2019). "Decreased GAPDH level in turn contributes to overactivation of four classic hyperglycemia-induced metabolite mechanisms, that is, the polyol pathway, the protein kinase C (PKC) pathway, AGEs pathway, and the hexosamine pathway." (PMID 26881021, 2016). "PPAR activated in retina increases oxidative stress and promotes DNA damage by inhibiting the activity of GAPDH, which then increases the flux into the four pathways induced by hyperglycemia." (PMID 25180070, 2014). "Since GAPDH is a glycolytic enzyme the reduction in bone-renal expression and hypoinsulinemia is consistent with the significant hyperglycemia measured in HYP mice." (PMID 24839967, 2014). "Increased ROS because of hyperglycemia inhibits activity of the glycolytic enzyme GAPDH, resulting in increased intracellular levels of the DAG precursor triose phosphate, which stimulates the synthesis of DAG from glucose via triose phosphate." (PMID 25180070, 2014). "Later work confirmed that hyperglycemia-induced overproduction of mitochondrial superoxide activates the four pathological pathways by inhibiting GAPDH." (PMID 25180070, 2014). "This process is based on that hyperglycemia, through the overproduction of free radicals by the mitochondrial electron transport chain, decreases the activity of the key glycolytic enzyme GAPDH." (PMID 22253615, 2012). "However, hyperglycemia causes excessive production of ROS and DNA single-strand breaks, stimulating PARP and leading to changes in GAPDH and thus reduced activity." (PMID 41155932, 2025). "The association between DKD and mitochondrial dysfunction stems from hyperglycemia-driven mechanisms, where increased ROS production from electron transport chain overload leads to DNA damage and reduced glyceraldehyde-3-phosphate dehydrogenase (GAPDH) activity." (PMID 39941397, 2025). "The ROS activation of PARP induced by hyperglycemia negatively impacts GAPDH activity." (PMID 40589740, 2025). "Moreover, hyperglycemia-induced overproduction of superoxide can enhance polyol pathway flux by inhibiting GAPDH-induced accumulation of glycolytic metabolites." (PMID 39148537, 2024).